IL6 (interleukin 6)
Diseases named in the same sentence as IL6 in open-access papers (continued):
Sharing a sentence is not in itself a finding about the gene and the disease.
tumor (continued). "We indeed measured high levels of IL-6 (1.17 ± 0.16 ng/ml) and IL-8 (2.98 ± 0.63 ng/ml) in the supernatant of 24 h 8505C culture (5 × 103 cells in 200 μl), supporting them as indicators of tumor progression and remission." (PMID 36463361, 2022). "Although the gDE7 immunization achieves partial tumor mass control in combination with D-1MT or DL-1MT in WT mice or when administered in IL-6-/- mice, the combination of gDE7 and 1MT in IL-6-/- mice further enhanced the antitumor effects, reaching total tumor rejection." (PMID 36405719, 2022). "Furthermore, to partially mimic the inflammatory tumor microenvironment, we introduced interleukin-6 (IL-6), which is the cytokine most reported to stimulate the growth of CRC cells." (PMID 35625868, 2022). "IL-6 is known to increase tumor angiogenesis and metastasis." (PMID 35547460, 2022). "M1 macrophages have the positive anti-tumor activity by upregulating the production of cytokines such as IL-6 and IL-1, which activate the T helper type 1 (Th1) reaction and further produce TNF-α, ROS, RNS, and other toxic substances to kill tumors and pathogenic microorganisms." (PMID 36313280, 2022). "In this tumor context, the activation of the immune system will lead to the secretion of anti-cancer cytokines, such as Interferon-gamma (INF-γ), TNF-α, and IL-6, and cell phagocytosis to eliminate the tumor, thus becoming a tool for the development of new treatments in cancer therapy." (PMID 36011024, 2022). "Despite presenting longitudinal imaging and biological data from a prospective trial and providing a potential link between IL-6 and tumor hypoxia in HNSCC patients treated by chemoradiation, there are some limitations, especially the limited sample size and absent external validation." (PMID 34773163, 2022). "In a mouse cancer model, knockout of IL-6 delays tumor development." (PMID 35672862, 2022). "IL-6 is a principle factor in the practical crosstalk between tumor cells and CAFs in the TME." (PMID 35740551, 2022). "Both IL-1 and IL-6 may enhance inflammation by recruiting immune cells to the area where the tumor is developing." (PMID 35887263, 2022). "The association between IL-6 expression and the overall survival of patients with PAAD was further evaluated to determine whether if its high level could play a role in tumor development." (PMID 35630552, 2022). "Another study also validated these results as DHMEQ inhibited 3D invasion of breast carcinoma cells through inhibition of matrix metalloproteinase (MMP), a peptidase important for extracellular matrix degradation in the tumor microenvironment, along with inhibition of IL-6." (PMID 36531159, 2022). "Inhibition of IL-6 or its receptors in a CAC-induced mouse model revealed a decreased tumor burden." (PMID 36140220, 2022). "The primary sources of IL-6 are tumor cells, MDSC, TAM, fibroblasts and CD8+ T cells." (PMID 36172343, 2022). "A master inducer of STAT3 activation in tumor and inflammatory cells is IL-6." (PMID 35993361, 2022). "Targeting neutrophil or inflammatory cytokines IL-1A and IL-6 could be potential therapies to restore anti-tumor immune reaction in PCPs." (PMID 36389809, 2022). "Moreover, mast cells inhibit tumor cell growth, apoptosis, diffusion, and inflammation by releasing cytokines, including IL-1, IL-4, IL-6, TNF-α, and chondroitin sulphate." (PMID 36430483, 2022). "Increased IL-6 secretion was ultimately shown to lead to IL-6-mediated Janus activated kinase (JAK) activation in tumor cells with subsequent downstream phosphorylation and activation of the transcription factor signal transducer and activator of transcription 3 (STAT3)." (PMID 35965494, 2022). "In the intestinal tract, tumor-associated bone marrow cells secrete IL-23, which affects the polarization of Th17 cells, followed by the production of IL-17A, IL-21, TNF-α, and IL-6, which induce a tumor-promoting inflammatory response and promote CC development." (PMID 36147322, 2022).
tumor (continued). "Moreover, tumour immunity, such as the inflammatory response, IL6/JAK/STAT3 signalling and IL2/STAT5 signalling, was prominently enriched in parental HCC cells." (PMID 36275751, 2022). "In a previously established mouse model, it was demonstrated that granulocyte-macrophage colony-stimulating factor (GM-CSF), IL-6, VEGF, and other tumor-associated cytokines could promote the accumulation and migration of MDSCs." (PMID 35757756, 2022). "Moreover, TAMs, specifically M1, are the main producers of IL-6, which plays a key role in modulating both tumor progression and immune escape through multiple mechanisms." (PMID 35742933, 2022). "Thus, anti-IL-6 treatment mimics the effect of N6L by decreasing immunosuppressive cells in the tumour microenvironment and increasing CD8+ tumour infiltration." (PMID 36077801, 2022). "The expression of TNF, VEGFA, and IL6 in the transplanted tumor cells could be regulated by using Celastrol, and the expression trends were consistent with the in vitro model." (PMID 36506508, 2022). "In various tumor types, continuous NF-κB signaling pathway activation in CAFs facilitates tumor progression and triggers inhibitory immune cell infiltration by secreting IL6, IL8, and other inflammatory molecules." (PMID 36032075, 2022). "Prior reports have also provided critical insights into the epigenetic mechanisms that govern the IL-6-induced generation of cancer stem cells, which are a subset of chemo-resistant tumor cells that drive cancer metastasis." (PMID 35757000, 2022). "Furthermore, immune cells, particularly macrophages, contribute to this metabolic adaptation by secreting interleukin-6 (IL-6) in the tumor microenvironment, phosphorylating thereby PGK1 and enhancing glycolysis in GBM cells." (PMID 35912242, 2022). "In addition, inhibition of IL-6 expression in CAFs or JAK2/STAT3 pathway in GC cells can impair the peritoneal metastasis of tumor induced by CAFs in vivo." (PMID 36591515, 2022). "Finally, anti-PD-L1 treatment in mice showed that blockade of PD-L1 significantly reversed tumor immune escape mediated by IL6-induced EVs." (PMID 35692503, 2022). "Blocking IL-6 inhibited tumor proliferation and increased T cell function in a LKB1-mutated mouse model, suggesting that aberrant cytokine signaling could be a promising immunotherapeutic strategy in selected patients." (PMID 35646638, 2022). "Moreover, in agreement with previous reports, coculture with TASCs resulted in increased proliferation of EpCAM+ tumor cells, mediated by IL-6, and higher invasive capacity." (PMID 35454931, 2022). "IL-6 is involved in the progression of many tumors and it is an important cytokine in tumor." (PMID 36591515, 2022). "Similarly, IL-6 is a cytokine released by a tumor, which, by binding to its receptor IL-6R, influences both cancer cell survival and cachexia." (PMID 36078078, 2022). "However, in an investigation of the relationship between IL-6 and the TIME, our study found that IL-6 expression was positively linked with PD-L1 expression and negatively correlated with CD8+ TILs in tumor tissues of patients with NSCLC." (PMID 35550592, 2022). "Tumor infiltrating myeloid cells produce tumorigenic, pro-inflammatory cytokines (IL-6, IL-23, TNFα and IL-1) but, oddly enough, also anti-inflammatory cytokines (IL-10, TGFβ) as well as molecules with immune suppressive functions (Arginase1, VEGF, peroxinitrite and Indoleamine 2-3 dioxygenase)." (PMID 35237269, 2022). "Furthermore, IL-6 was shown to be necessary to maintain the activation status of stromal fibroblasts and the inflammatory microenvironment required for optimal tumor growth." (PMID 35965494, 2022). "Through this transformation, CAF may secret VEGF or interleukin–6 (IL–6), thus affecting angiogenesis and tumor growth." (PMID 35743115, 2022). "Finally, increased levels of serum IL-6 have been correlated with poor prognosis, tumor size, and disease status." (PMID 35681689, 2022).
tumor (continued). "Pro-inflammatory cytokines secreted by tumor cells or stromal cells, such as interleukin 6 (IL6), IL1β and C-C motif chemokine ligand 2 (CCL2), can induce phenotypic changes in tumor cells, recruit bone marrow-derived cells and form an inflammatory environment." (PMID 36158661, 2022). "For instance, the ligand for receptor activator of nuclear factor kappaB or IL-6 could accelerate angiogenesis, bone destruction, and tumor growth." (PMID 35911705, 2022). "Among tumor-related factors involved in the generation of MDSCs and their recruitment from bone marrow to tumor microenvironment are mediated by granulocyte–macrophage colony-stimulating factor (GM-CSF), IL-6, indoleamine 2,3-dioxygenase (IDO) and chemokines (e.g. CCL26, CXCL12, CXCL8)." (PMID 35589776, 2022). "Due to IL-6’s pleiotropic nature, it has also been shown to play critical roles in tumour growth, angiogenesis, and metastasis of different cancer types by activating signalling pathways after assembly and dimerization with its receptor IL-6R and glycoprotein 130 (gp130)." (PMID 36439165, 2022). "Interleukin-6 (IL-6) is a pro-inflammatory cytokine released by cancerous cells in the tumor microenvironment and plays a vital role in the differentiation and expansion of tumor cells." (PMID 36547062, 2022). "Notably, our data demonstrated that RT provided protection against the activation of STAT3, overabundance of IL-6, and oxidative stress-mediated muscle atrophy in tumor-bearing mice." (PMID 35847939, 2022). "Moreover, high expression of IL-6 was relevant to large tumor size (P = 0.0123) and TNM stage (P = 0.0002) in 108 cases of OSCC patients." (PMID 35513871, 2022). "Moreover, iCAF was activated by tumour‐secreted IL‐1 and then increased the secretion of IL‐6, IL‐11 and LIF." (PMID 36282889, 2022). "A recent in vivo study using an acute lymphoblastic leukemia mouse model showed that IL-6 could suppress chemotherapy-induced anticancer immunity by tumor microenvironment (TME)." (PMID 36497467, 2022). "Ablation-induced increase in IL-6 has been previously reported in clinical studies and in preclinical models, and successful blockade of this cytokine has curbed ablation induced distant tumor growth." (PMID 35857766, 2022). "IL-6 can be expressed both by the tumor, stromal and immune compartments in PCa." (PMID 36338516, 2022). "Interestingly, TAMs can also induce the stem cell phenotype in GBM tumor cells by releasing mediators like IL-6 and IL-1β, or through juxtacrine signaling." (PMID 36338705, 2022). "IL-6 is involved in tumour angiogenesis and IL-6 levels are directly correlated with VEGF levels." (PMID 36140343, 2022). "CAF in tumor microenvironment promotes GC progression through IL-6/JAK2/STAT3 signal transduction." (PMID 36591515, 2022). "We observed that in the absence of STAT3, IL-6 induced the activation of STAT1 and its target genes suggesting that IL-6 derived from the tumor microenvironment may activate both STAT1 and STAT3 target genes in HCC tumor cells." (PMID 35267462, 2022). "Similarly, through their ability to secrete inflammatory molecules such as IL-1, IL-6 and TNFα, CAFs participate in inflammation-mediated tumor progression." (PMID 35493456, 2022). "Additionally, we tested the CSF cytokine (e.g., IL-6, IL-10) levels in the tumor-bearing mice after Trojan bacteria injection." (PMID 36050316, 2022). "Therefore, we proved that inhibition of Sox4 also can obviously prevent the growth and inflammation of tumor bearing mice mediated by IL-6." (PMID 35513871, 2022). "Furthermore, as reported in other studies, this indicates the key role of IL-6 and IL-8 in autocrine signaling for tumor cells and regulation of the immune response against the tumor." (PMID 35703345, 2022). "However, it is also known that CD163 expression is induced by pro-inflammatory cytokines such as IL-6, glycolytic metabolites produced by proliferating tumor cells such as lactate, and hormones including glucocorticoids." (PMID 35269507, 2022).
tumor (continued). "In addition, we suggested a new mechanism of LCN2 in the tumor microenvironment through which IL-6, a powerful cytokine in CAC, is able to specifically increase LCN2 promoter activity under control of NF-kB activation." (PMID 35470375, 2022). "In addition, CAFs produce more IL-6 than fibroblasts in normal tissues preventing tumor cell apoptosis through a STAT3-dependent mechanism and enhancing angiogenesis." (PMID 36419156, 2022). "We found that spleen IL-6 levels were significantly higher in memantine pretreated tumor free group p = 0.0204 ) We also found that high dose memantine treated tumor free group (G3a) has significantly lower genome-wide DNA methylation levels when compared to tumor control group (G1) p = 0.0012." (PMID 36326318, 2022). "Several studies have addressed the role of IL-6 in tumour cell growth in vitro." (PMID 35980113, 2022). "For instance, inflammatory cytokines produced by tumor cells, such as tumor necrosis factor‐α, interleukin (IL)‐6, and IL‐8, are thought to contribute to muscle wasting and atrophy by inducing oxidative stress in skeletal muscles and activating muscle degradation pathways." (PMID 36338593, 2022). "A long list of tumor-borne, often proinflammatory factors, including interleukin-6 (IL-6), parathyroid hormone–related protein (PTHrP), leukemia inhibitory factor (LIF), zinc α-glycoprotein, or growth differentiation factor-15 (GDF-15), trigger CAC in mouse models." (PMID 35210363, 2022). "This may help to overcome tumor resistance to these forms of effector mechanism and lead to higher secretion of IL-6 and IFN-γ." (PMID 36551328, 2022). "However, during CRC carcinogenesis, tumors secrete factors, such as TGF-β, prostaglandin E2 (PGE2), IL-6, IL-10, and IL-1β, resulting in the accumulation of MDSCs in peripheral blood and at the tumor site." (PMID 36436127, 2022). "Moreover, in vivo, miR-155-5p in exosomes secreted by M2 TAMs can promote the expression of interleukin-6 (IL-6) in tumor cells, thereby inhibiting the T-cell immune response." (PMID 35592338, 2022). "In addition, adipose-derived stem cells (ADSCs) promoted tumor initiation and accelerated tumor growth through IL-6 production." (PMID 35924148, 2022). "Moreover, the paracrine effect of IL-6 produced by MDSCs can directly increase the survival, proliferation, and drug resistance of tumor cells." (PMID 36389684, 2022). "The E2F and IL6 families are classical tumor signaling pathways." (PMID 36111242, 2022). "We found NSCLC with a low baseline concentration of IL-6 in plasma specimens or tumor tissues could derive more benefit from ICIs based on the patient cohort." (PMID 35550592, 2022). "Other studies reported that IL-6/Notch signals could cooperatively stimulate tumor metastasis and drug-resistance." (PMID 36466926, 2022). "Interleukin 6 is described as an important cytokine in tumor initiation and progression." (PMID 36172343, 2022). "Furthermore, high numbers of IL-6+ cells were evident in the lamina propria of the tumour tissue from wild-type mice." (PMID 35793807, 2022). "Finally, the secretion of IL-6 by endothelial cells in the tumor microenvironment is also capable of activating MMP9 and causing tumor remodeling." (PMID 36497411, 2022). "IL-6/STAT3 signaling pathway has been shown to regulate TAMs polarization in tumor." (PMID 35193986, 2022). "TNF-α and IL-6 sustain the survival of tumor cells that reach blood and lymphatic circulation." (PMID 36294305, 2022). "Similarly to N6L, the number of infiltrated CD8+ T cells within the tumour increased in anti-IL6-treated tumour sections compared to the control." (PMID 36077801, 2022). "The role of IL-6 in regulating CSCs was also studied in other types of human cancer (e.g., glioblastoma), where targeting it led to cellular apoptosis and reduction in tumor growth." (PMID 35659296, 2022).
tumor (continued). "In B16F-10 melanoma cells, andrographolide inhibits the expression of granulocyte-macrophage colony-stimulating factors and pro-inflammatory cytokines such as TNF-α, IL-1β and IL-6 genes, inhibits the activation of NF-κB and AP-1 to promote apoptosis of tumor cells." (PMID 36238575, 2022). "IL6 is a cytokine involved in numerous biological processes including immune response, inflammation, and embryonic development, and it is also a key factor in tumor development and progression." (PMID 35401700, 2022). "IL-6 is also involved in the formation of vasculature and a key factor for tumour growth." (PMID 36396670, 2022). "IL-6 was discovered in 1986 as a B cell stimulatory factor; it is a multifunctional and pleiotropic cytokine that is secreted by several cell types such as monocytes, lymphocytes, keratinocytes, and endothelial and tumor cells." (PMID 34773163, 2022). "In addition, Wongchana and Palaga found a direct regulatory effect of Notch on IL-6 activation at the transcript level in immune cells, and another study found that IL-6 was also a mediator of crosstalk between fibroblasts and tumor cells in the CRC TME." (PMID 36466926, 2022). "Therefore, pro-inflammatory cytokines such as IL-1 members and IL-6 secreted from GBM tumor cells aggravate tumor-promoting inflammation and GBM growth." (PMID 35572545, 2022). "Tumor-associated macrophages are abundant in the TME and impede anti-cancer immune responses by generating inflammatory cytokines, such as IL-12, IL-1b, TNF-α, and IL-6." (PMID 36298592, 2022). "However, IL-6 is known to act ambiguous in relation to cancer, both promoting tumor growth and impeding tumor growth by immune stimulation." (PMID 34347128, 2022). "In addition, the elevation of serum levels of IL6 or activation of IL6-signaling pathways in the tumor tissue correlates significantly with the shortened overall survival and time to progression in PCa." (PMID 35885510, 2022). "Although some studies have shown very promising results in targeting IL-6–IL-6R axis with Tocilizumab, concern remains, if manipulation of IL-6 may also support tumor growth as it has been discussed in the past." (PMID 34347128, 2022). "Moreover, quercetin decreased IL-6/IL-1β in the rats with early HCC for initiating the immune response to kill tumor cells." (PMID 36615387, 2022). "This review discussed selected relevant soluble factors [transforming growth factor-beta (TGFβ), interleukin-6 (IL-6), IL-10, IL-23] and cellular components of the innate immunity, as drivers of tumor progression, immunosuppression, and angiogenesis within the PCa-TME." (PMID 36338516, 2022). "Based on the present data from a prospective exploratory imaging trial, we could demonstrate a strong association between IL-6 plasma levels and PET imaging-derived tumor hypoxia dynamics in patients undergoing chemoradiation for locally advanced HNSCC." (PMID 34773163, 2022). "However, the activation of GPER1 hinders its anti-tumor capability by raising the intracellular Amphiregulin, IL6, IL8, antiapoptotic proteins, and invasivity promoting factors." (PMID 35337112, 2022). "Consistent with the view that the ROBO3/AXL regulatory network promoted tumor aggressiveness through the IL-6/STAT3 axis, we observed significantly reduced expression of AXL and p-STAT3 in dCas9-ROBO3 tumors, whereas tumors derived from LacZ showed robust expression of AXL and p-STAT3." (PMID 35993361, 2022). "Moreover, IL-6 in the tumor microenvironment promotes tumor progression resistance to chemo- and radiotherapy through the JAK/STAT3 signaling pathway." (PMID 36362245, 2022). "IL-6-/- mice treated with gDE7 and D-1MT had a 73% survival rate and 52% remained tumor-free till the end of the observation period (D60), whereas animals treated with gDE7 and DL-1MT had a 52% survival rate and 47% were tumor-free." (PMID 36405719, 2022).